NLRP3 (NLR family pyrin domain containing 3)
Diseases named in the same sentence as NLRP3 in open-access papers (continued):
Sharing a sentence is not in itself a finding about the gene and the disease.
acute kidney injury (144 papers, 2011 to 2026). Sudden and sustained deterioration of the kidney function characterized by decreased glomerular filtration rate, increased serum creatinine or oliguria. "This alteration led to the activation of the NLRP3 inflammasome and pyroptosis in endothelial cells, consequently exacerbating the inflammatory response associated with sepsis-induced acute kidney injury." (PMID 40308771, 2025). "Conversely, p16 overexpression has been associated with NLRP3 inflammasome activation in acute kidney injury models via oxidative stress regulation." (PMID 40079088, 2025). "Overexpression of tubular NLRP3 has been linked to inflammation, fibrosis, and poor tubular repair in mouse models of mild or severe acute kidney injury." (PMID 40027896, 2025). "Animal studies have shown that inhibiting either TXNIP or NLRP3 can prevent acute kidney injury caused by rhabdomyolysis-induced ischemia-reperfusion injury." (PMID 39045044, 2024). "Consistent with our results, the RIP3-mediated activation of the NLRP3 inflammasome was also observed in caspase-8-deficient dendritic cells treated with LPS and acute kidney injury." (PMID 38911926, 2024). "Nlrp3 Deficiency Mitigates Acute Kidney Injury Induced by Lipopolysaccharide through the inhibition of renal inflammation and ferroptosis in mice." (PMID 38740765, 2024). "Previous studies have implicated the activated NLRP3 inflammasome in the pathogenesis of many kidney diseases, including acute kidney injury (AKI), crystal-related nephropathy, and CKD." (PMID 38720901, 2024). "In our previous study, macrophage mobility inhibitory factor inhibitor therapy ameliorated SAP-associated acute kidney injury by inhibiting the NLRP3 inflammasome signaling pathway." (PMID 36316322, 2022). "Nod-like receptor protein 3 (NLRP3), as an inflammatory regulator, has been implicated in acute kidney injury (AKI)." (PMID 34716316, 2021). "The role of NLRP3 has been underlined in the various causes of acute kidney injury (AKI), a pathology characterized by high morbimortality and risk of transition toward chronic kidney disease (CKD)." (PMID 34099830, 2021). "Treatment of SNx animals with theracurmin improved structural and functional manifestations of cardiac injury associated with renal failure and also attenuated cardiac NLRP3 inflammasome activation and mature IL-1β release." (PMID 28000751, 2016). "Additionally, activation of the NLRP3 inflammasome in renal tubular epithelial cells has been linked to ischemia-reperfusion-induced acute kidney injury." (PMID 39045044, 2024). "The podocytes, resident visceral epithelial cells that constitute the glomerulus, can express all the inflammasome components of NLRP3 that seems to be involved in the inflammatory mechanisms that underlies acute kidney injury (AKI) and chronic kidney disease (CKD)." (PMID 34381495, 2021). "It has been shown that the NLRP3 inflammasome has been linked to disease such as atherosclerosis, acute and chronic respiratory diseases, Alzheimer’s disease, traumatic brain injury, acute kidney injury (AKI), chronic kidney disease (CKD), and cancer." (PMID 33806292, 2021). "Furthermore, recent reports have implicated that the NLRP3 inflammasome is an important contributor to inflammation and tissue damage during acute kidney injury, chronic kidney disease, and kidney inflammation and fibrosis." (PMID 28194406, 2017). "The NLRP3 inflammasome has been implicated in various kidney diseases, including acute kidney injury (AKI) and chronic kidney disease (CKD)." (PMID 31694192, 2019). "LncRNA NEAT1 can play an important role in the pathogenesis of acute kidney injury by activating the NLRP3 inflammasome." (PMID 39973927, 2025). "Ultimately, SA mitigates kidney injury in IRI mice by suppressing renal failure through inhibition of the AKT/NLRP3 signaling pathway." (PMID 40260531, 2025).
acute kidney injury (continued). "This proteolytic event triggers NLRP3 inflammasome activation, driving inflammation and renal injury in I/R-induced acute kidney injury (AKI)." (PMID 40909173, 2025). "We investigated the potential correlation between miR‐223 and NAcHT, LRR, and PYd domain‐containing protein 3 (NLRP3) in the context of renal ischemia‐reperfusion injury (RIRI), which is a leading cause of acute renal failure with significant mortality rates." (PMID 39252576, 2024). "They found that activation of renal NLRP3 inflammasome and increased cytokines in the heated group led to renal impairment, suggesting a link between extreme heat and acute kidney injury via NLRP3 inflammasome activation." (PMID 39840312, 2024). "The increased expression of NLRP3 in patients with severe AP also causes elevated kidney MPO levels and triggers a cytokine cascade, contributing to renal damage and acute kidney injury (AKI) in severe AP models." (PMID 39596901, 2024). "PANX-1 mediates necrosis-induced NLRP3 inflammasome activation in macrophages during acute kidney injury." (PMID 39075542, 2024). "Knockouts of caspase-1 or NLRP3 result in the attenuation of acute kidney injury induced by ischemia-reperfusion injury." (PMID 38740765, 2024). "The NLRP3 inflammasome was involved in the pathogenesis of many kidney diseases, including acute kidney injury and CKD." (PMID 38063077, 2024). "It is reported that Fc reduced albuminuria, alleviated renal failure, and relieved podocyte injury in db/db mice by inhibiting the NLRP3 inflammasomes." (PMID 37215100, 2023). "It has been shown that the interaction between C/EBPβ and TFAM activates NLRP3/caspase-1 and promotes the development of acute kidney injury." (PMID 37624173, 2023). "VD/VDR signaling down-regulated the expression of pyroptosis associated markers NLRP3, GSDMD-N, Cleaved Caspase-1 and mature IL-1βin AKI models, and partially alleviated cisplatin induced acute kidney injury by inhibiting pyroptosis mediated by NF-κB." (PMID 37483634, 2023). "We aimed to study the effect of S-nitroso glutathione (SNG) on acute kidney injury (AKI) in septic rats by regulating nucleotide oligomerization domain-like receptor protein 3 (NLRP3)." (PMID 37396949, 2023). "Mdivi-1, an inhibitor of Drp1, alleviates acute kidney injury (AKI) by suppressing NLRP3 inflammasome activation." (PMID 37488647, 2023). "lncRNA PVT1 modulates NLRP3-mediated pyroptosis in septic acute kidney injury by targeting miR-20a-5p." (PMID 35132346, 2022). "Thioredoxin-interacting protein (TXNIP) downstream of the IRE1α pathway has been proved to regulate pyroptosis through the TXNIP/NLRP3 pathway in acute kidney injury, hepatocellular injury, preeclampsia, and other diseases." (PMID 36552271, 2022). "While they did find that caspase 1 knockout mice were protected against cisplatin-induced apoptosis and renal failure, follow up studies provided weak evidence that inhibition of NLRP3 activity protected against cisplatin-induced AKI." (PMID 35806229, 2022). "Our previous study also demonstrated how β-HB supplementation ameliorates cisplatin-induced acute kidney injury (AKI) by inhibiting NLRP3 inflammasome activation and the cGAS-STING pathway." (PMID 36235648, 2022). "NLRP3 is the most widely studied inflammasome, which can be activated through classical or non-classical pathways and participates in the pathogenesis of acute kidney injury and chronic kidney disease." (PMID 35692535, 2022). "Another recent study proposed that knockdown of lncRNA DLX6-AS1 inhibits HK-2 cell pyroptosis via regulating the miR-223-3p/NLRP3 pathway in lipopolysaccharide-induced acute kidney injury." (PMID 35132346, 2022). "In another study of I/R-induced ARF, it was concluded that acute kidney injury causes the NLRP3 inflammasome to be released by directly affecting the renal tubular epithelium, which leads to the activation of caspase-1, causing inflammatory cell infiltration and the activation of cytokines." (PMID 34135984, 2021).
acute kidney injury (continued). "Extracellular ATP promotes NLRP3, an inflammasome complex, that enhances cytokine production and tissue injury in acute kidney injury (AKI)." (PMID 34067880, 2021). "One study demonstrated that glycerol-mediated rhabdomyolysis-induced acute kidney injury (RIAKI) is ameliorated in NLRP3 knockout (KO) mice compared to control mice." (PMID 33202867, 2020). "In line with this, several previous studies have indicated that the Nlrp3 inflammasome activation plays an important role in the pathogenesis of acute kidney injury." (PMID 33552083, 2020). "The purpose of this trial was to examine the role of NLRP3-mediated inflammation and oxidative stress injury in promoting the progressive renal failure observed in a model of ceftriaxone calcium crystal nephropathy." (PMID 32695257, 2020). "In recent years, it has been intensively reported that NLRP3 inflammasome/Caspase-1/IL-1β signaling pathway was involved in renal tubular lesion during acute kidney injury." (PMID 31616439, 2019). "We evaluated the role of inflammasome-independent NLRP3 in renal tubular cells and assessed the value of NLRP3 as a therapeutic target for acute kidney injury (AKI)." (PMID 30483252, 2018). "In contrast to these results, we and others previously found that the Nlrp3 inflammasome enhanced acute kidney injury and dysfunction following ischemia reperfusion injury." (PMID 24454932, 2014). "While human coronaviruses, including SARS-CoV-2, are known to activate the NLRP3 inflammasome in renal tissues and contribute to acute kidney injury, the spatial and temporal dynamics of this activation in specific tubular epithelial subtypes remain poorly understood (52, –, 54)." (PMID 41334910, 2025). "Furthermore, inhibition of NLRP3 inflammasome activation improves renal function in mice with acute kidney injury by upregulating mitochondrial autophagy." (PMID 39604027, 2024). "For patients with fibrosis, it may be possible to predict that the NLRP3 inflammasome will be involved in the management of renal failure." (PMID 38114914, 2023). "According to a recent study, MCC950 inhibits the NLRP3 inflammasome, which prevents acute renal failure by increasing hypoxia-inducible factor 1 and BCL2/adenovirus E1B interacting protein-mediated mitophagy, which lessens the effects of iohexol-induced apoptosis and renal injury." (PMID 38114914, 2023). "While, genetic NLRP3 deficiency mice are resistant to ischemic but not cisplatin-induced acute kidney injury and fibrosis." (PMID 36175910, 2022). "In addition, knockdown of KCNQ1OT1 would reduce the activation of NLRP3 inflammasome in acute kidney injury." (PMID 36278219, 2022). "This study identified the renoprotective properties of HQH against CYP-induced acute kidney injury and the underlying mechanisms, including its antioxidant and anti-inflammatory activities, as well as its effects on NF-κB/MAPK signalling and NLRP3 inflammasome." (PMID 34693876, 2021). "Previous studies had indicated that NLRP3 may provide a potential therapeutic target for the treatment of contrast media induced acute kidney injury." (PMID 30691208, 2019). "NLRP3 inflammasome has also been shown to be a mediator of ischemic acute kidney injury, as evidenced in a model of NLRP3 knockout mice which were protected from acute kidney injury." (PMID 30691208, 2019). "Moreover, there is growing evidence that renal NLRP3 inflammasome activation contributes to tubular cell damage in acute kidney injury." (PMID 31616439, 2019). "Furthermore, NLRP3 knockout protects unilateral ureteral occlusion mice and renal ischemia/reperfusion-induced acute kidney injury mice from renal tubular damage and interstitial inflammation." (PMID 28194406, 2017). "Furthermore, NLRP3 deletion studies in mice undergoing unilateral nephrectomy suggested that NLRP3 plays a vital role on contributing to contrast media-induced acute kidney injury and cell apoptosis as confirmed by both in vitro and in vivo studies." (PMID 27721494, 2016).
acute kidney injury (continued). "NLRP3 knockout would also protect against ischemic acute kidney injury." (PMID 26132490, 2015). "This interaction restrains redox-related damage in septic acute kidney injury (AKI) by suppressing NLRP3 inflammasome-mediated pyroptosis." (PMID 40307577, 2025). "The NLRP3 inflammasome is a significant factor in inflammation and tissue damage during acute kidney injury (AKI), CKD, renal inflammation, and fibrosis." (PMID 35120573, 2022). "NLRP3 inflammasome has been found to be activated through mROS/TXNIP/NLRP3 signaling pathway in ischemic acute kidney injury (AKI)." (PMID 36304156, 2022). "Indeed, another study shows that danger signals from necrotic tubular epithelial cells could activate the NOD-like receptor protein 3 (NLRP3) inflammasome in macrophages through the TLR2/caspase 5/Panx1 axis during acute kidney injury (AKI)." (PMID 36555574, 2022). "In a model of cell sepsis‐induced acute kidney injury (S‐AKI), Mdivi‐1 treatment inhibited mitochondrial fragmentation which prevented the release of mitochondrial contents and decreased NLRP3 activation in renal tubular epithelial cells." (PMID 34337844, 2021). "The concept of inflammasome-independent NLRP3 implication in fibrosis was also studied in renal tubular cells destroyed in acute kidney injury (AKI)." (PMID 33172097, 2020). "Collectively, we demonstrated that NLRP3 inflammasome mediated CI-AKI through modulating the apoptotic pathway, which provided a potential therapeutic target for the treatment of contrast media induced acute kidney injury." (PMID 27721494, 2016). "In acute kidney injury, PINK1-Parkin-mediated mitophagy can reduce mitochondrial ROS and subsequent NLRP3 inflammasome activation." (PMID 41513612, 2026). "In acute kidney injury (AKI), various insults—including contrast agents, sepsis, rhabdomyolysis, and chemotherapeutic drugs—stimulate NLRP3 activation through danger signals like ATP and reactive oxygen species, leading to tubular cell necrosis and inflammation." (PMID 40648980, 2025). "Studies have shown that activation of NLRP3 (NLR family pyrin domain containing 3) inflammasomes during acute kidney injury can promote the formation of CaOx crystals, thereby exacerbating acute kidney injury." (PMID 40612664, 2025). "Pyroptosis emerged via NLRP3 inflammasome activation and GSDMD/GSDME cleavage, exacerbating inflammation and overt renal failure." (PMID 41301789, 2025). "Acute and chronic respiratory diseases, traumatic brain injury, acute kidney injury (AKI), and chronic kidney disease (CKD) also reported the involvement of the NLRP3 inflammasome." (PMID 35639261, 2022). "Recent key studies have identified that NLRP3-mediated pyroptosis was activated by CEBPB, which contributed to the promotion of acute kidney injury." (PMID 36248187, 2022). "In a model of rhabdomyolysis-induced acute kidney injury (RIAKI), activation and assembly of NLRP3 inflammasomes preceded infiltration of renal immune cells such as macrophages." (PMID 32175320, 2020). "For example, after ischemic acute kidney injury, NLRP3 expression is increased, and NLRP3−/− vs. wild-type mice exhibit significantly lower acute tubular necrosis and apoptosis scores in the kidney." (PMID 32867797, 2020). "Most of the studies regarding the role of NLRP3 have been performed on acute kidney injury (AKI) models, and fewer were done using models of CKD, due to the deficit of rodent models that could mimic the human CKD." (PMID 30271792, 2018). "Utilizing database-based enrichment analysis, coupled with in vitro and in vivo pharmacological experiments, we discovered that inhibiting AKT/NLRP3 inflammasome activation attenuated inflammatory responses and pyroptosis, thereby ameliorating RIR-induced acute kidney injury." (PMID 40260531, 2025).
acute kidney injury (continued). "Hederasaponin C, a natural product, effectively inhibits lipopolysaccharide (LPS)-induced acute kidney injury in mice by specifically targeting Toll-like receptor 4 (TLR4) and modulating the phosphatidylinositol 4,5-bisphosphate (PIP2)/NF-κB/NLRP3 signaling pathway." (PMID 38740765, 2024). "In conclusion, this study shows that the inhibition of Calpain 1 and 2 activity by calpeptin plays a nephroprotective role in ischemia/reperfusion-induced acute kidney injury by suppressing AIM2 and NLRP3 inflammasome activation and by upregulating Klotho protein." (PMID 35155498, 2022). "In conclusion, treatment with JGE has protective effects against renal dysfunction induced by I/R injury via inhibition of the NLRP3 signaling pathway, indicating that JGE should be considered an effective Korean traditional medicine for treating acute kidney injury and renal remodeling." (PMID 34135984, 2021). "In the murine acute kidney injury model, a lack of NLRP3 resulted in protected kidney functions, attenuated inflammation, and increased survivability of mice." (PMID 31427885, 2019). "In a study by Lin and coworkers, which investigated the pathogenic mechanism of contrast-induced acute kidney injury (CI-AKI), NLR family pyrin domain-containing 3 (NLRP3)-driven inflammation came into focus." (PMID 40497970, 2025). "In a contrast-induced acute kidney injury (CI-AKI), the activation of PINK1-Parkin-mediated mitophagy ameliorates tissue damage and suppress apoptosis in renal tubular epithelial cells (RTECs) through the inhibition of mitochondrial ROS and NLRP3 inflammasome activation." (PMID 32630319, 2020). "The activation of NLRP3 is involved in renal disorders, such as chronic kidney disease (CKD), diabetic nephropathy (DN), and acute kidney injury (AKI), by both canonical and non-canonical pathways." (PMID 33584697, 2020).